KLHL22 (kelch like family member 22)
Description:
Substrate-specific adapter of a BCR (BTB-CUL3-RBX1) E3 ubiquitin ligase complex required for chromosome alignment and localization of PLK1 at kinetochores. The BCR(KLHL22) ubiquitin ligase complex mediates monoubiquitination of PLK1, leading to PLK1 dissociation from phosphoreceptor proteins and subsequent removal from kinetochores, allowing silencing of the spindle assembly checkpoint (SAC) and chromosome segregation. Monoubiquitination of PLK1 does not lead to PLK1 degradation. The BCR(KLHL22) ubiquitin ligase complex is also responsible for the amino acid-stimulated 'Lys-48' polyubiquitination and proteasomal degradation of DEPDC5. Through the degradation of DEPDC5, releases the GATOR1 complex-mediated inhibition of the TORC1 pathway. It is therefore an amino acid-dependent activator within the amino acid-sensing branch of the TORC1 pathway, indirectly regulating different cellular processes including cell growth and autophagy.
Synonyms: FLJ14360; KELCHL
Tractability: Small molecule: it belongs to a druggable protein family. PROTAC: ubiquitination databases record sites on it; its protein half-life has been measured.
Gene: Protein-coding gene on chromosome 22 (20,441,519 to 20,496,893, reverse strand). Ensembl gene ENSG00000099910.
Subcellular location: Cytoplasm, cytosol; Cytoplasm, cytoskeleton, microtubule organizing center, centrosome; Cytoplasm, cytoskeleton, spindle; Nucleus; Lysosome
Subcellular location (Human Protein Atlas): Cytokinetic bridge; Microtubules; Mitotic spindle; Vesicles
Pathways (Reactome):
Immune System: Antigen processing: Ubiquitination & Proteasome degradation
Metabolism of proteins: Neddylation
Gene Ontology:
Molecular function: 14-3-3 protein binding; protein binding; ubiquitin-like ligase-substrate adaptor activity
Biological process: cell division; cellular response to amino acid stimulus; cellular response to L-leucine; mitotic sister chromatid segregation; mitotic spindle assembly checkpoint signaling; negative regulation of autophagy; negative regulation of type I interferon production; positive regulation of cell growth; positive regulation of T cell activation; positive regulation of T cell mediated immune response to tumor cell; positive regulation of TORC1 signaling; proteasome-mediated ubiquitin-dependent protein catabolic process; protein monoubiquitination; ubiquitin-dependent protein catabolic process; protein ubiquitination
Cellular component: centrosome; Cul3-RING ubiquitin ligase complex; cytoplasm; cytosol; intercellular bridge; lysosome; mitotic spindle; nucleus; polar microtubule; spindle
Genetic constraint (gnomAD): Loss-of-function variants: 17 observed, 54.1 expected, observed/expected ratio (o/e) 0.31, 90% interval 0.21 to 0.47. The upper end of that interval is the gene's LOEUF score, 0.47, which puts it in group 2 of 6, group 1 being the genes least tolerant of losing a copy. Missense variants: 568 observed, 833.25 expected, observed/expected ratio (o/e) 0.68, 90% interval 0.63 to 0.73. Synonymous variants: 344 observed, 354.62 expected, observed/expected ratio (o/e) 0.97, 90% interval 0.89 to 1.06.
Homologues: Orthologues: chimpanzee KLHL22 (99% identical), dog KLHL22 (98% identical), pig KLHL22 (96% identical), rat Klhl22 (95% identical), guinea pig KLHL22 (95% identical), mouse Klhl22 (95% identical), tropical clawed frog klhl22 (70% identical), zebrafish klhl22 (59% identical). Paralogues in human: KLHL9 (30% identical), KLHL13 (30% identical), KLHL36 (29% identical), KLHL26 (29% identical), KLHL32 (27% identical), KLHL14 (27% identical), KLHL20 (27% identical), KLHL15 (26% identical), KLHL17 (26% identical), KLHL28 (26% identical), KLHL1 (25% identical), KLHL6 (25% identical), and 42 more.
Diseases named in the same sentence as KLHL22 in open-access papers:
KLHL22 is named in the same sentence as 4 diseases in open-access papers, as found by Europe PMC text mining. Sharing a sentence is not in itself a finding about the gene and the disease. The quoted sentences say what the papers report.
colorectal cancer (2 papers, 2023). A primary or metastatic malignant neoplasm that affects the colon or rectum. "In clinical colorectal cancer patients, there was a downregulation of KLHL22 in tumor infiltrating T cells." (PMID 36733484, 2023). "Hence, KLHL22 governed excessive T cell suppression via regulation of PD-1 expression in colorectal cancer." (PMID 36733484, 2023).
breast carcinoma (1 paper, 2020). "Moreover, the expression of KLHL22 is significantly negatively correlated with DEPDC5 in patients with breast cancer." (PMID 32296023, 2020). "Therefore, pharmacological interventions targeting KLHL22 may have therapeutic potential for relevant diseases, such as breast cancer and age-related diseases." (PMID 32296023, 2020).
cancer (4 papers, 2018 to 2022). A tumor composed of atypical neoplastic, often pleomorphic cells that invade other tissues. "In cancer cells, KLHL22 degrades DEPDC5 and releases inhibition of GATOR1 on mTORC1 in response to amino acid availability." (PMID 36440598, 2022). "In cancer cells and in aging C. elegans, KLHL22 promotes mTORC1 activation by degrading DEPDC5 and releasing inhibition of GATOR1 on mTORC1." (PMID 36440598, 2022). "The kelch-like family member 22 (KLHL22) is a tumour suppressor protein involved in the development/progression of several cancers." (PMID 33080952, 2020). "Only KLHL29, KLHL38, and KLHL22 had hazard ratios or inverse hazard ratios >2 in the same direction with three cancer types." (PMID 30647843, 2018). "KLHLs with significant hazard ratios or inverse hazard ratios for four cancer types regardless of direction were KLHL14, KLHL22, KLHL29, KLHL32, and KLHL36." (PMID 30647843, 2018).
tumor (2 papers, 2023). "Therefore, deficiency of KLHL22 resulted in PD-1 upregulation, conferring to suppression of T cells-mediated antitumor response and facilitated tumor development." (PMID 36733484, 2023).